OR8H3 (olfactory receptor family 8 subfamily H member 3)
Description:
Odorant receptor.
Synonyms: OR11-172
Tractability: Small molecule: it belongs to a druggable protein family. Antibody: UniProt places it where antibodies can reach, with medium confidence; UniProt predicts a signal peptide or a membrane-spanning region; its Gene Ontology location is reachable by antibodies, with medium confidence.
Gene: Protein-coding gene on chromosome 11 (56,122,373 to 56,123,311, forward strand). Ensembl gene ENSG00000181761.
Subcellular location: Cell membrane
Pathways (Reactome):
Sensory Perception: Expression and translocation of olfactory receptors
Gene Ontology:
Molecular function: olfactory receptor activity; G protein-coupled receptor activity
Biological process: G protein-coupled receptor signaling pathway; sensory perception of smell; detection of chemical stimulus involved in sensory perception of smell
Cellular component: plasma membrane; membrane
Genetic constraint (gnomAD): Missense variants: 374 observed, 364.22 expected, observed/expected ratio (o/e) 1.03, 90% interval 0.94 to 1.12. Synonymous variants: 139 observed, 136.2 expected, observed/expected ratio (o/e) 1.02, 90% interval 0.89 to 1.17.
Homologues: Orthologues: chimpanzee OR8H3 (97% identical), macaque OR8H3 (91% identical), rat Or8h10 (73% identical), mouse Or8h10 (71% identical), mouse Or8h9 (71% identical), rat Or8h6 (71% identical), rat Or8h10c (71% identical), mouse Or8h6 (70% identical), rat Or8h9 (70% identical), mouse Or8h7 (70% identical), rat Or8h7 (70% identical), mouse Or8h8 (69% identical), and 2 more. Paralogues in human: OR8H2 (92% identical), OR8H1 (89% identical), OR8I2 (57% identical), OR5B21 (51% identical), OR5F1 (51% identical), OR5A1 (51% identical), OR5B12 (51% identical), OR8D4 (50% identical), OR5M8 (49% identical), OR8U1 (49% identical), OR5B2 (49% identical), OR8B4 (49% identical), and 84 more.